CD81 (CD81 molecule)
Diseases named in the same sentence as CD81 in open-access papers (continued):
Sharing a sentence is not in itself a finding about the gene and the disease.
COVID-19 (14 papers, 2021 to 2026). A disease caused by infection with severe acute respiratory syndrome coronavirus 2. "Our findings were remarkable, especially considering a report that detected the Spike protein using different technologies including Western-blot analysis after enriching CD9/CD81/CD63 EV subpopulations in COVID-19 patients." (PMID 39569406, 2024). "Considering the overall median fluorescence intensity (MFI) for specific EV markers (i.e., tetraspanins CD63, CD9 and CD81) we observed that only EV-specific tetraspanin CD81 was significantly higher in COVID-19 patients than controls (P<0.05)." (PMID 37207201, 2023). "An increase in CD19+, CD19+CD38+IgMlow, CD19+CD38+CD27highIgMhigh, and CD19+CD81+ lymphocytes and decrease in the lymphocyte count and NK cell percentage were correlated with severity in COVID-19-infected children." (PMID 38813014, 2023). "Tetraspanin monoclonal antibodies (anti-CD9, anti-CD63 and anti-CD81) have been demonstrated to inhibit the COVID-19 entry stage." (PMID 36101528, 2022). "Therefore, it is essential to investigate the importance of CD81 in patients with COVID-19 and Neuro-COVID." (PMID 34531741, 2021). "Our analyses also suggest a differential miRNA expression between CD63+/CD81+/CD9+ serum small‐EVs from mildly and severely ill Covid‐19 hospitalized patients, which will require further evaluation." (PMID 34122779, 2021). "Regardless of the tissue type, we saw consistent increases in genes such as B2M, CD81, GNAS, HLA.B, HSPA1A, HSPB1, and SERPING1 in COVID-19 lungs." (PMID 35233546, 2022). "Flow cytometry confirmed the enrichment of EV specific markers CD63, CD81 and CD62P in COVID-19 (+) patient LEVs compared to healthy donors and COVID-19 (+) patient SEVs." (PMID 36564503, 2022). "Our results suggest enrichment for EV specific markers CD63, CD81, and CD62P and procoagulant PS in COVID-19 (+) patient plasma EVs compared to healthy donors." (PMID 36564503, 2022). "In this study, we found several exosomes including CD9, CD31, CD40, CD45, CD41b, CD42a, CD62P, CD69, CD81, CD105, and HLA-DRDPDQ in the plasma of COVID-19-recovered pregnant women were significantly less abundant than the control group." (PMID 35647028, 2022). "Western blotting analysis displayed EV specific tetraspanin markers (CD63 and CD81) expression of healthy donor SEVs/LEVs and COVID-19 (+) patient SEVs/LEVs and EDP as negative control." (PMID 36564503, 2022). "Because ACE2 is present in tetraspanin-enriched microdomains, where it clusters with other glycoproteins, such as CD9, CD81, and TMPRSS2, we also established assays to define whether anti-IgM antibodies against any of these proteins were present in COVID-19 sera." (PMID 35349483, 2022). "Interestingly, the most upregulated gene, namely CD81, is specifically required for the formation of lamellipodia in migrating DCs, suggesting an active role for DC activation, maturation, migration, and survival related to type I IFN-mediated response in the activation of immune cells in COVID-19." (PMID 41596638, 2026).
glioma (14 papers, 2009 to 2025). A benign or malignant brain and spinal cord tumor that arises from glial cells (astrocytes, oligodendrocytes, ependymal cells). "In this study, we identified CD81 as a potential biomarker of GBM radioresistance with the analysis of upregulated genes in human glioma radioresistant cell lines U251R and T98G in comparison with U251 cells." (PMID 33919192, 2021). "Consistent with the in vitro experimental results, knockdown of CD81 further enhanced radiation-induced growth suppression of glioma xenografts of both U251R and T98G cells." (PMID 33919192, 2021). "In order to analyze two different populations of glioma cells and hUCBSC inco-cultures, we used flow cytometry using two different markers, namely CD81 forhUCBSC and GFAP for glioma cells." (PMID 21455311, 2011). "This targeting ability is attributed to specific surface moieties retained from the parent cells, including tetraspanins (CD9, CD63, CD81), integrins (e.g., αvβ3, α6β4), and phosphatidylserine, which interact with overexpressed receptors on the glioma endothelium and tumor cells." (PMID 40725021, 2025). "In this manner, CD81-mediated DNA repair later in the genesis of glioma might become more important for tumor cell survival." (PMID 36203458, 2022). "Here we identified fatty acid synthase (FASN), a key lipogenic enzyme which is highly expressed in malignant glioma cells, to be elevated in CD63- and CD81-positive EVs in glioma patient plasma samples, opening vital opportunities to sort brain tumor-specific EVs." (PMID 32178271, 2020). "Notably, functional loss of tetraspanin CD9 led to a marked increase in EGF-stimulated tumor cell invasion, consistent with recent analyses of CD81 and its associated EWI-2 protein complexes in gliomas." (PMID 26377974, 2015). "CD9 regulated glioma progression via calcium signaling and synaptic pathways, interacting with ITGB1 and CD81." (PMID 40406701, 2025). "We identified several targets involved in glioma growth and migration, specifically CXCL1, CD81, TPT1, Gas6 and AXL proteins." (PMID 19558675, 2009). "The characterisation of relevant protein markers and targets for glioma are identified with the ATLAS project and confirms the relevance of genes such as CD81, and InhibinB." (PMID 19558675, 2009). "These stem cells up-regulate the DNA damage repair system; next, when a low-grade glioma evolves into a GBM, CD81-mediated DNA repair could prove to be very important in cancer cell survival." (PMID 39684236, 2024). "In glioma, a study exploring EVs released by proneural, and mesenchymal glioma stem cells (GSCs) identified that proneural GSC-derived EVs lacked canonical EV-based tetraspanin markers such as CD9, CD63, and CD81, while they were abundant in mesenchymal GSC-derived EVs." (PMID 38760427, 2024).
prostate carcinoma (14 papers, 2015 to 2025). A carcinoma that arises from epithelial cells of the prostate gland. "In prostate cancer, using CD81 and prostate-specific antigen (PSA) biomarkers, it was shown that prostate cancer patients had higher levels of exosomal CD81 and PSA." (PMID 36675253, 2023). "In prostate cancer, higher levels of exosomal CD81 and prostate-specific antigen were observed, which could distinguish prostate cancer patients from benign prostatic hyperplasia and healthy subjects." (PMID 36109501, 2022). "Because it had a direct association with several exosome markers, such as CD9, CD81 and CD82, we carried out exosome extraction and analysis for the prostate cancer cell lines PC3 and Du145 cells with EWI‐2 CRISPR/Cas9 knockout as well as the overexpression of EWI‐2 in PC3 cells." (PMID 33605506, 2021). "Indeed, we found that the number of clusters expressed by specific combinations of either intra-vesicular (STAT3 and CyclinD1) or surface proteins (ERBB3, ALK, and CD81) allowed us to significantly discriminate the patients with prostate cancer from the individuals with hyperplasia." (PMID 39120316, 2024). "Several tetraspanins such as CD81, CD9, tetraspanin-6 and tetraspanin-8 were enriched in prostate cancer versus control samples." (PMID 26196085, 2015). "Notably, previous studies have shown that CD81, METTL3, STEAP1, and TRIM28 contributed to the progression of prostate cancer." (PMID 37958805, 2023). "EVs from individuals with prostate cancer typically include cancer-related proteins such as CD9, CD81, and TSG101, as well as Annexin A2, Fatty Acid Synthase (FASN), and a prostate cancer-specific biomarker termed FOLH1 (Prostate Specific Membrane Antigen or PSMA)." (PMID 36059497, 2022). "The exosomal (CD9- CD81-SCARB2) (average enrichment 2.40) and lysosomal (CTSD- LAMP2- CTSZ- SPNS1- PSAP) (average enrichment 4.15) proteins were also enriched in exosomes from prostate cancer patients." (PMID 26196085, 2015). "Furthermore, in EVs isolated from patients with prostate cancer, higher levels of CD81 and prostate-specific antigen (PSA) were detected, which could discriminate prostate cancer patients from benign prostatic hyperplasia and healthy individuals." (PMID 39336143, 2024). "Manipulation of the AR signalling axis alters the protein cargo in S‐EVs in LNCaP prostate cancer cells, and that the tetraspanin CD9 has been shown to be significantly more abundant in EVs from DHT‐treated cells when comparison with other S‐EVs markers including: TSG101, Alix, CD63 and CD81." (PMID 34434533, 2021). "Plasmatic EVs expressing both CD81 and PSA were significantly higher in prostate cancer patients compared to either healthy controls or patients with BPH, reaching 100% specificity and sensitivity in distinguishing prostate cancer patients from healthy individuals." (PMID 33924671, 2021).
multiple myeloma (12 papers, 2016 to 2025). "In hematologic malignancies, CD81 has mostly been studied in multiple myeloma where its expression on plasma cells is associated with worse progression free survival (PFS) and overall survival (OS)." (PMID 27566555, 2016). "Previously, in Paiva's study, it was found that in multiple myeloma, the detection of CD81 positivity on plasma cells was a poor prognostic factor." (PMID 37309539, 2023). "In previous studies, CD81 was found to be present in the plasma cells of patients diagnosed with multiple myeloma, resulting in faster relapses, and a worse prognosis for progression-free survival (PFS) and overall survival (OS)." (PMID 37309539, 2023). "Regarding cell surface markers, it is well known that CD81 indicates a poor prognosis in myeloma patients, whereas CD117 is correlated with a positive prognosis." (PMID 35886877, 2022). "It was reported that, through the study of 225 newly-diagnosed multiple myeloma patients, patients harboring more CD81+ in tumor cell plasma had a less differentiation state, dismal survival, and higher chemoresistance." (PMID 33919192, 2021). "Prognostic value of CD81 expression in multiple myeloma and its use as a marker in minimal residual disease (MRD) in chronic lymphocytic leukemia (CLL) are well established." (PMID 27566555, 2016). "In this study, the immunophenotype was retrospectively analyzed in 131 patients who received initial treatment for plasma cell myeloma (PCM) and the relationships of CD81 and CD117 with the clinicopathologic characteristics and prognosis were further evaluated." (PMID 30358164, 2018). "Therefore, the role of CD81 in blast cell homing needs to be determined in AML, as similar effects have been described in multiple myeloma." (PMID 27566555, 2016). "In multiple myeloma, detection of CD81 positive plasma cells was an independent negative prognostic factor for PFS and OS." (PMID 27566555, 2016). "In addition, an increase in CD200 (hsc and pre-BI), Nanog (hsc and pre-pro-B), sXBP-1 (pre-pro-B and pro-B), Oct3/4 (pre-BI), and CD81 (pre-BI) and a decrease in CD362 (hsc and pro-B) are noted only in MGUS or SMM, showing clonal hematopoiesis extending to premalignant stages of myeloma." (PMID 36752202, 2023). "The cell and EV lysates from myeloma line RPMI 8226 was positive for CD9 but negative for CD63 and CD81." (PMID 35318648, 2022).
lymphoma (10 papers, 2011 to 2025). A malignant (clonal) proliferation of B- lymphocytes or T- lymphocytes which involves the lymph nodes, bone marrow and/or extranodal sites. "Several knockouts illustrate their biological functions such as infertility (CD9/CD81), lymphoma development (CD37), immunological deficiency (CD81), or renal insufficiency (CD151)." (PMID 37835445, 2023). "The etiological association between SMZL and chronic infection for hepatitis C virus is commonly related in Southern Europe, and the development of lymphoma under these conditions appears to be associated with activation of CD81 in B-cells by chronic stimulation of the virus E2 glycoprotein." (PMID 32746790, 2020). "Our data suggest that the high CD81 expression on B-lymphoma cell lines contributes to cell migration of those lymphoma cells." (PMID 34824296, 2021). "B-lymphoblastic leukemia/lymphoma with TCF3::PBX1 fusion has also been reported to overexpress CD58 and CD81 when compared with cases of B-lymphoblastic leukemia/lymphoma without cytogenetic alterations or with other cytogenetic abnormalities." (PMID 40227608, 2025). "In order to rule out sequestration of CD21 and CD81 by endogenous CD19 in Raji cells we used OCI-LY3 cells (a lymphoma cell line) that do not express CD19." (PMID 33735268, 2021). "B-lymphoblastic leukemia/lymphoma with BCR::ABL1 fusion has also been reported to exhibit a decreased expression of CD9 and CD81 when compared with cases of B-lymphoblastic leukemia/lymphoma without cytogenetic alterations or with other cytogenetic abnormalities." (PMID 40227608, 2025). "Anti-CD81 mAbs are not yet in the clinic but there are anti-tetraspanin mAbs in early clinical development, such as the anti-CD37 BI 836826 currently developed in leukemia and lymphoma." (PMID 37046846, 2023). "For example, CLL/SLL cells are positive for CD5, CD23, CD200, dim for CD20 and CD81, and negative for FMC-7; in MCL, lymphoma cells are positive for CD5, and negative for CD23; and in FL, lymphoma cells are positive for CD10 and CD20, and negative for CD34 and TdT." (PMID 34879826, 2021).
osteosarcoma (10 papers, 2019 to 2026). A usually aggressive malignant bone-forming mesenchymal neoplasm, predominantly affecting adolescents and young adults. "McNamara and colleagues described the distribution and co-localization of CD63 and CD81 in lipid rafts and EVs secreted by U-2 osteosarcoma cells." (PMID 41304773, 2025). "Based on osteosarcoma (OS) cell line, we demonstrated that a combination of CD81 and CD63 antibody on ZNI chip yielded the greatest amount of total EVs, with an extra sensitive limit of detection (LOD) of ~104 particles mL-1." (PMID 34527582, 2021). "The expression of CD81 was inhibited in osteosarcoma cells using siRNA after which cell proliferation, migration and invasion were assessed." (PMID 31494861, 2019). "CD63 and CD81 were detected in the exosomes produced from osteosarcoma cells by flow cytometry." (PMID 32673448, 2020). "In addition, we found that osteosarcoma cell proliferation, migration and invasion were decreased after CD81 inhibition, and that the phosphorylation of Akt and Erk was suppressed." (PMID 31494861, 2019).
atherosclerosis (9 papers, 2015 to 2025). A disease characterized by the build-up of fatty material and calcium deposition in the arterial wall resulting in partial or complete occlusion of the arterial lumen. "To test if FN associates with sEV markers in atherosclerosis, we investigated the spatial association of FN with sEV markers using the sEV-specific marker CD81." (PMID 37645762, 2023). "Since CD81 is highly expressed in the human endothelium during early atherosclerosis, HCV infection might also be able to cause inflammation in the coronary vessels leading to CHD via the TGF-β/SMAD pathway activation." (PMID 36292250, 2022). "More importantly, MR imaging using CD81-MPIO as a contrast agent may provide a noninvasive tool to explore expression of CD81 and its corresponding gene functions linked to the genesis, development, prognosis of atherosclerosis, and susceptibility to antiatherosclerosis drugs." (PMID 26266263, 2015). "The goal of this study is to investigate the feasibility of using CD81- (Cluster of Differentiation 81 protein-) targeted microparticles of iron oxide (CD81-MPIO) for magnetic resonance imaging (MRI) of the murine atherosclerosis." (PMID 26266263, 2015). "Previous studies have showed that endothelial CD81 is an ideal molecular marker for evaluating the atherosclerosis prior to the full-blown inflammatory response." (PMID 26266263, 2015). "Additionally, the inflammatory milieu, characterized by elevated production of cytokines and altered expression of CD81 and CD46, aligns with previous findings that associate these markers with the pathogenesis of atherosclerosis and IHD55,56." (PMID 39975917, 2025). "In this study, DNMT1 expression was down-regulated in atherosclerosis, MI, and IS patients (signifying hypomethylation) and positively correlated with expression of markers in TCR signaling (i.e, CD81, CD3)." (PMID 27213032, 2015).
hepatitis C (9 papers, 2012 to 2023). "Furthermore, elevated levels of CD81 are associated with inflammation and the severity of fibrosis, indicating that CD81 may be a potential biomarker for hepatitis C diagnosis and treatment response." (PMID 30987213, 2019). "On the other hand, it has been reported that in hepatitis C virus infection, multiple receptor molecules, including SR-B1, low-density lipoprotein receptor, CD81, claudin-1, occluding, epidermal growth factor receptor, and EphA2 are involved in its process." (PMID 34372540, 2021). "CD81, another exosomal marker from the tetraspanin family, plays a critical role in hepatitis C attachment and/or cell entry." (PMID 25695100, 2015). "In the current study, soluble CD81 levels were significantly higher in patients with hepatitis C compared to patients with HCV infection and normal ALT levels." (PMID 22355327, 2012). "A final conclusion that soluble CD81 levels are mostly derived from inflammatory processes in patients with hepatitis C cannot be drawn from the results of the current study." (PMID 22355327, 2012). "During hepatitis C virus infection, the ubiquitin ligase, Casitas B-lineage lymphoma proto-oncogene B forms a complex with another cellular factor, calpain-5 and the hepatitis C virus entry factor CD81 to support the virus entry into liver cells." (PMID 32544190, 2020). "Moreover, in patients cured from hepatitis C, CD81 levels normalized to levels found in healthy subjects." (PMID 22355327, 2012).
leukemia (9 papers, 2021 to 2025). A malignant (clonal) hematologic disorder, involving hematopoietic stem cells and characterized by the presence of primitive or atypical myeloid or lymphoid cells in the bone marrow and the blood. "Several studies have shown that CD81 plays a role in cancer cell proliferation, invasion, and metastasis, particularly in leukemia." (PMID 41211316, 2025). "Seven leukemia-associated immunophenotype pattern (LAIP) markers, CD9, CD44, CD58, CD73, CD81, CD86, and CD123, were also included in the diagnostic panel." (PMID 39371707, 2024). "Genes that are overexpressed in both MPAL subtypes blast cells compared to other leukemias and healthy controls include CD81, and LMO2." (PMID 37845689, 2023). "To isolate blast-derived sEV from patients’ plasma, we developed a bioprinted microarray-based immunoassay using monoclonal antibodies (mAbs) specific for leukemia-associated antigens (LAAs) and mAbs specific for a mix of tetraspanins (CD9, CD63, and CD81)." (PMID 38137457, 2023). "Different studies have established a role for CD81 in leukemia cell engraftment, notably as a regulator for the re-entry of hematopoietic stem cells to quiescence, via a process implicating the Akt pathway." (PMID 37046846, 2023). "The expression of CD81 varies significantly according to the leukemia type." (PMID 37046846, 2023). "However, there have been few studies on the correlation between CD81 and leukemia, especially regarding whether CD81 can be used as a target for AML." (PMID 41211316, 2025). "As quality control of the system, transduction of leukemia cell lines expressing split-Cas9 with sgRNAs targeting CD19, CD81 or F11R strongly decreased the expression of the respective cell surface proteins." (PMID 37422628, 2023). "We tested this approach using tetraspanin CD81 as a pan-vesicular marker and CD34 as a marker for leukemia-derived EVs." (PMID 35008226, 2021).